RNU6-10P (RNA, U6 small nuclear 10, pseudogene)
Synonyms: RNU6-10
Gene: Small nuclear RNA gene on chromosome 7 (92,701,708 to 92,701,814, reverse strand). Ensembl gene ENSG00000206763.
Homologues: Orthologues: chimpanzee U6 (98% identical), mouse Gm25450 (97% identical), rat LOC120097296 (96% identical), guinea pig U6 (95% identical), rabbit U6 (92% identical), dog U6 (89% identical), macaque U6 (86% identical). Paralogues in human: RNU6-1 (97% identical), RNU6-15P (97% identical), RNU6-2 (97% identical), RNU6-3P (97% identical), RNU6-4P (97% identical), RNU6-5P (97% identical), RNU6-6P (97% identical), RNU6-9 (97% identical), RNU6-12P (96% identical), RNU6-13P (96% identical), RNU6-17P (96% identical), RNU6-18P (96% identical), and 1289 more.